IGF1 (insulin like growth factor 1)
Diseases named in the same sentence as IGF1 in open-access papers (continued):
Sharing a sentence is not in itself a finding about the gene and the disease.
endocrine disorder (62 papers, 1998 to 2026). "Growth hormone deficiency (GHD) is a pediatric endocrine disorder characterized by dysregulated growth hormone/insulin-like growth factor-1 (GH/IGF-1) axis activity and gut microbiota imbalance." (PMID 40520290, 2025). "The high concentrations of GH and insulin-like growth factor-1 (IGF-1) in the serum of patients with this rare endocrine disease affect their physiology and metabolism and cause a series of symptoms that seriously affect their health and quality of life." (PMID 40065992, 2025). "Given the potential risk of endocrinopathy and GH/IGF1 axis dysfunction, close monitoring of endocrine function, including IGF1 levels, should be considered especially in young, skeletally immature patients." (PMID 41375023, 2025). "Endocrine tests (e.g. serum IGF1 concentration) may point towards the basic endocrinopathy and narrow down the specific defect, such as IGF1 deficiency or IGF1 resistance." (PMID 32513286, 2020). "The lncRNA HOTAIR aggravated the endocrine disorders and granulosa cell apoptosis through competitive binding to miR-130a to upregulate the expression of IGF1." (PMID 33681369, 2021). "Consistent evidence from in vitro and in vivo studies demonstrate endocrine disorders, metabolic imbalance, and cardiovascular defects are all characterized by imbalance in the Insulin-like growth factor-1 (IGF-1) hormone and its affiliated signaling." (PMID 33807089, 2021). "We show that HOTAIR up‐regulates the expression of IGF1 and aggravates the endocrine disorders and granulosa cell apoptosis through competitive binding to miR‐130a in rat models of PCOS." (PMID 31733099, 2020). "LncRNA HOTAIR up‐regulates the expression of IGF1 and aggravates the endocrine disorders and granulosa cell apoptosis through competitive binding to miR‐130a in rat models of PCOS." (PMID 31733099, 2020). "No cases of severe endocrinopathy were detected, and no significant deficiencies in thyroid or adrenal axes were observed, but a decrease in insulin-like growth factor 1 (IGF1) levels was identified." (PMID 41375023, 2025). "IF diets may also benefit metabolic and endocrine disorders in PCOS by changing the circulating levels of Insulin-like Growth Factor-1 (IGF-1) and Insulin-like Growth Factor-Binding Protein 1 (IGFBP1)." (PMID 37242145, 2023). "Specific factors that intervene to favor this imbalance are metabolic acidosis, endocrine disorders involving the insulin/IGF-1 signaling, low testosterone levels, alterations in the renin–angiotensin–aldosterone system, systemic inflammation, and an abnormal hypothalamic appetite regulation." (PMID 34383112, 2022). "Twenty-six patients (83.87%) who presented normal IGF-1 concentrations and a normal response to the GHRH + arginine test were discharged from follow-up for a reduced risk of evolving into endocrinopathy, whereas endocrine follow-up was recommended for the five patients with subnormal GH stimulation." (PMID 30678118, 2019). "By demonstrating that HOTAIR up‐regulated the expression of IGF1 via competitive binding to miR‐130a in the rat models of PCOS, we provide insight into the mechanisms underlying the promotion effect of up‐regulated HOTAIR expression in the endocrine disorders and granulosa cell apoptosis." (PMID 31733099, 2020). "A repeated measurement of the IGF-1 concentration of this cat about 6 months later again revealed a high value (915 ng/mL) in an otherwise clinically healthy cat, without any evidence of cardiac or endocrine disease or any clinicopathological abnormalities." (PMID 37756097, 2023).
neurological diseases (38 papers, 2010 to 2025). "Changes in brain insulin and IGF1 signaling have been associated with neurological diseases, however the molecular factors regulating brain insulin sensitivity remain uncertain." (PMID 37463909, 2023). "In the brain, IGF-1 regulates the proliferation and differentiation of multiple CNS resident cells and has been implicated in several neurological disorders." (PMID 33117368, 2020). "Interestingly, a subset of ASD-associated genes that were recovered after IGF-1 treatment has previously been linked to neurological disorders such as MFF, a mitochondrial gene that is associated with Leigh-like encephalopathy, and Nup93, a nucleoporin important in neuronal differentiation." (PMID 32591005, 2020). "Known for its neuroprotective properties, cGP has shown great potential for therapeutic applications, particularly in treating neurological disorders by modulating insulin-like growth factor 1 (IGF-1) homeostasis." (PMID 39590698, 2024). "Small, IGF-1 mimetic, cyclic peptides have advantages over IGF-1, representing a novel strategy of pharmaceutical discovery for neurological disorders." (PMID 35203315, 2022). "Research in rodent models has demonstrated rescue of pathophysiological and behavioral abnormalities when IGF-1 was administered by different routes, and several clinical studies have shown safety and promise of efficacy in neurological disorders of the CNS." (PMID 35203315, 2022). "The concentrations of IGF-1 in the cerebral spinal fluid have been correlated with brain growth in autistic children, while low values of IGF-1 have been reported in a number of serious neurologic diseases of children." (PMID 32498399, 2020). "In the first study, in 11 children younger than five years we found low CSF IGF-1 concentrations compared to age-matched controls with neurological disorders." (PMID 28954393, 2017). "These assumptions implicate that GH and IGF-1 should be considered for the prevention and treatment of various neurological diseases." (PMID 29149058, 2017). "There were 110 ADRs in 68 patients, including 19 general disorders/administration site conditions, 18 nervous system disorders, 16 musculoskeletal/connective tissue disorders and two events of increased IGF-1 levels." (PMID 28161880, 2017). "We conclude that there are now great hopes for the therapeutic use of IGF-1 for some neurological disorders (particularly ASD)." (PMID 28954393, 2017). "Reinforcing its pluripotent role in both endocrine and neuronal health status, Igf1 was represented across multiple pathways, including “nervous system development”, “cell growth and proliferation”, and “neurological disease”." (PMID 22934110, 2012). "Tthrough literature research, we found that VAV3 may exhibit anti-infective and anti-inflammatory properties, and IGF1 may play a neuroprotective role in nervous system diseases." (PMID 40626048, 2025). "We elucidate how IGF-1 may be involved in molecular signaling defects that occurs in MetS-related neurodegenerative disorders and highlight the importance of IGF-1 as a potential therapeutic target in MetS-related neurological diseases." (PMID 36691085, 2023). "IGF-1 also has been tested for treatment of neurological diseases." (PMID 37621718, 2023). "This understanding may speed up the progress in clinical translation of IGF-1 for developing new neuroprotective therapies towards neurological diseases with glutamate excitotoxicity as a common pathological pathway." (PMID 35203315, 2022). "In conclusion, it is expected that IGF-1 and derived peptidomimetics with pleiotropic effects will provide a new, supplemental therapy that will target specific excitotoxic processes and brain cell types that contribute to different neurological diseases." (PMID 35203315, 2022).
neurological diseases (continued). "Brain-derived neurotrophic factor (BDNF)-overexpressing hNSPCs, glial cell line-derived neurotrophic factor (GDNF)-overexpressing hNSPCs, and insulin-like growth factor 1 (IGF-1)-overexpressing hNSPCs have all been shown significant therapeutic effects on neurological disorders." (PMID 34827135, 2021). "Moreover, the relevance of oxidative stress and the potential benefit of such factors as BDNF, GDNF and IGF-1 in multiple other neurological diseases (e.g. ALS and Huntingdon's chorea) indicate obvious potential applications of GDAsBMP in other settings." (PMID 24477866, 2014). "Thus, IGF-1 is a promising therapeutic option for the treatment of various neurological disorders through regulation of multiple neuroprotective signaling pathways, including Ras/Erk1/2, PI3K/MAPK/Akt/mTOR, Ca2+/CaMK II and IV, CREB, C/EBPβ, and GSK3B/NF-kB/NLRP3." (PMID 36691085, 2023). "Despite significant scientific advances supporting the restorative effects of IGF-1, the precise molecular pathways leading to its neuroprotective effects remain unclear and more studies are needed to accurately understand the role of IGF-1 in MetS-related neurological diseases." (PMID 36691085, 2023). "Recent studies suggest that IGF-1 and its receptor IGF-1R are involved in the pathogenesis of neurological diseases." (PMID 41256775, 2025). "Numerous studies indicate roles for IGF-1/IGF-1R signaling in the pathogenesis and progression of neurological disorders and show that their expression is differentially modulated by CNS insult." (PMID 33117368, 2020). "While IGF-1 has been reported to cross the blood-brain barrier, its lack of success in clinical trials for neurological disorders has been disappointing." (PMID 39516073, 2024). "The bioavailability of IGF-1 and IGF-2 and their binding proteins (IGF-BP2 and IGF-BP3) could play an important role in the prevention and treatment of several neurologic disorders." (PMID 29149058, 2017).
prostate (35 papers, 2003 to 2025). "Identifying the regulation of stromal AR in IGFBP3 expression in Gli1-lineage FB is intriguing, suggesting an underlying mechanism for androgen-mediated IGF1 signaling activation in prostate oncogenesis." (PMID 36323713, 2022). "Administration of apigenin to transgenic adenocarcinoma of the mouse prostate (TRAMP) mice induced a reduction in the levels of insulin-like growth factor 1 (IGF-1) levels." (PMID 30823649, 2019). "Another study showed the neuroprotective effect of IGF1 and erythropoietin combination treatment via intranasal delivery in the middle cerebral artery occlusion model." (PMID 24959881, 2014). "First, the involvement of insulin and IGF-1 in colorectal carcinogenesis has been supported by experimental and clinical studies." (PMID 23349764, 2013). "Moreover, high IGF1 level contributes to colorectal carcinogenesis, while inhibiting IGF1 suppresses CRC cell growth and metastasis." (PMID 34075028, 2021). "Finally, metabolic abnormalities can lead to insulin (but also to IGF1 and E2)-mediated prostate inflammation and hyperplasia." (PMID 33692752, 2021). "Some anti-angiogenesis related genes were essentially down-regulated in PC3 cells, i.e. MMP2, TNF-alpha, CCL11 and the potent pro-angiogenic factor IGF1 (9 fold down-regulation) which is deeply involved in prostate carcinogenesis and identified as autocrine proliferation stimulus for hPCa cells." (PMID 24681516, 2014). "A previous study indicated that finasteride could potentially inhibit the expression of Insulin-like Growth Factor 1(IGF-1) by suppressing the activity of c-JUN within fibroblasts in benign prostate tissue, leading to a reduction in the synthesis and secretion of IGF-1." (PMID 39944628, 2025). "In etiological approaches, the regulation and metabolism of insulin and IGF-1 are correlated, sharing homologous molecular structures, while many studies have shown the impact of high circulating IGF-1 levels on prostate carcinogenesis." (PMID 22792092, 2012). "IGF-1 can signal through IGF-1R, IR, or IGF-1R+IR hybrid receptors; however, IGF-1 is unlikely to be involved in our model because KPTIRKO mice resisted HFD-induced kidney injury." (PMID 33400689, 2021).
retinopathy (35 papers, 2011 to 2026). "In extremely preterm infants, high early postnatal plasma glucose levels and signs of insulin insensitivity were associated with lower IGF1 levels and increased retinopathy of prematurity severity." (PMID 33004691, 2020). "Previously, large litter size was reported to be associated with low circulating IGF-1 and worse retinopathy in pups in an oxygen-induced retinopathy model." (PMID 28195189, 2017). "However, in patients with adequate blood glucose control, elevated serum IGF-1 levels are associated with higher cumulative incidence of severe retinopathy." (PMID 35248150, 2022). "High sensitivity to oxygen results in a series of changes such as upregulation of VEGF and IGF-1 may cause ROP-like retinopathy." (PMID 34963467, 2021). "Recent data has demonstrated that overweight/obese children with retinopathy had significantly higher insulin-like growth factor 1 (IGF-1) SDS (-0.66 ± 0.9 vs. 0.03 ± 1.3, p = 0.04) compared to overweight/obese individuals without retinopathy." (PMID 37033164, 2023). "The only significant intergroup difference was their GH and IGF-1 levels, enabling us to precisely investigate their effects on retinopathy development." (PMID 35248150, 2022). "At P12, liver Igf1 mRNA expression was decreased by more than 2-fold in the streptozotocin-treated oxygen-induced retinopathy group, before plasma glucose and IGF1 levels changed." (PMID 33004691, 2020). "The plasma IGF1 protein level at P17 was significantly decreased in the hyperglycemic oxygen-induced retinopathy versus normoglycemic oxygen-induced retinopathy groups." (PMID 33004691, 2020). "IGF1 treatment of the hyperglycemic oxygen-induced retinopathy mice reduced the retinal avascular retinal area compared with vehicle control at P17 (P = 0.027)." (PMID 33004691, 2020). "Recently, insulin-like growth factor 1 (IGF1) has been shown to play a role in the pathophysiology of this retinopathy." (PMID 24523937, 2014). "In addition, local upregulation of IGF1 has been shown to trigger blood‒retinal barrier breakdown, and accordingly, humans with retinopathy with marked gliosis exhibited upregulation of IGF1R expression." (PMID 38252153, 2024). "Based on these findings, we hypothesized that the early restoration of IGF-1 levels may play a protective role against severe retinopathy in premature infants." (PMID 37322452, 2023). "In contrast, patients with IFG who had proliferative retinopathy had similar GH and IGF-1 levels and traditional risk factors for retinopathy compared to those without proliferative retinopathy." (PMID 35248150, 2022). "Our data revealed that GH or IGF-1 may play a crucial role in the development of proliferative retinopathy and may influence the progression of retinopathy." (PMID 35248150, 2022). "We hypothesize that this may be because serum IGF-1 and IL-6 are involved in the development of retinopathy." (PMID 36568065, 2022). "The data reveals that GH and IGF-1 might play a crucial role in the development of proliferative retinopathy and influence its progression." (PMID 35248150, 2022). "However, Igf1 and Igfbp3 mRNA expression in the liver was decreased more than 2-fold in the hyperglycemic oxygen-induced retinopathy pups (both P < 0.0001)." (PMID 33004691, 2020). "Recombinant human IGF1 was injected to assess the effect on glucose and retinopathy." (PMID 33004691, 2020). "The mRNA expression profile at P17 was comparable to the expression at P12, with more than a 2-fold decrease of Igf1 and Igfbp3 in the hyperglycemic oxygen-induced retinopathy versus normoglycemic oxygen-induced retinopathy groups (both < 0.0001); Igfbp1 mRNA expression was the same in each group." (PMID 33004691, 2020). "Similarly, greater early macronutrient intake and growth velocity with higher insulin-like growth factor 1 (IGF-1) and insulin-like growth factor binding protein 3 (IGFBP3) levels have been associated with decreased retinopathy of prematurity severity." (PMID 31892145, 2019).
retinopathy (continued). "To assess whether IGF1 supplementation can promote revascularization and therefore decrease neovascularization in oxygen-induced retinopathy in the setting of disturbed insulin signaling, we injected recombinant IGF1 starting at P12 when revascularization of the avascular retina begins." (PMID 33004691, 2020). "The plasma levels of IGF1 protein were slightly decreased, but not significantly, in hyperglycemic oxygen-induced retinopathy pups (P = 0.25)." (PMID 33004691, 2020). "We hypothesize that IGF-1 can accelerate the progression of retinopathy from non-proliferative to proliferative and shorten the duration of non-proliferative retinopathy." (PMID 35248150, 2022).
kidney disease (28 papers, 2009 to 2026). "Despite the proposed mechanistic role of IGF-1 in DKD, results of clinical studies investigating the association between IGF-1 levels and kidney disease are inconclusive." (PMID 37438734, 2023). "In conclusion, this study provides evidence that elevated IGF-1 levels or the ratio of IGF-1/IGFBP-3 is associated with a higher risk of kidney disease progression and all-cause mortality." (PMID 37438734, 2023). "Moreover, as reported in a recent meta-analysis, IGF1 rs35767 increases the risk of renal disease." (PMID 35205271, 2022). "Conceivably, facilitating partial IGF1 signaling in the podocyte could have therapeutic potential in the treatment of kidney diseases, as is currently being assessed in other disease situations." (PMID 38706850, 2024). "Indeed, previous studies have established a connection between urinary excretion of insulin like growth factors and renal disease activity; as a result, increased levels of IGF-1 in severe CKD patients may not be directly linked to renal excretion." (PMID 37438734, 2023).
heart disease (27 papers, 2011 to 2025). "In this regard, some evidence associates the decline in IGF-1 expression with heart disease." (PMID 37372424, 2023). "Another circulating factor implicated in cardiac disease is insulin-like growth factor 1 (IGF-1)." (PMID 29760740, 2018). "Although this work is descriptive, it provides a clear insight of the impact that partial IGF-1 deficiency on the heart and establishes this experimental model as suitable for studying cardiac disease mechanisms and exploring therapeutic options for patients under IGF-1 deficiency conditions." (PMID 28806738, 2017). "Then, we compared IGF-1 myocardial expression in healthy non-alcoholic donors used as controls with hypertensive donors, donors with chronic alcohol consumption and donors with other causes of cardiac disease separately." (PMID 25984322, 2013). "The reduction of the levels of insulin-like growth factor-1 (IGF-1) was strictly linked to a higher risk of developing HF also in older patients without heart disease." (PMID 39519069, 2024). "In contrast, other evidence suggests that increased IGF-1 expression is involved in heart disease." (PMID 37372424, 2023). "Additionally, IGF-1 expression is increased in the presence of cardiac disease and dysfunction." (PMID 29232706, 2017). "Multiple hormones (e.g., angiotensin II, aldosterone), growth factors (e.g., IGF-1) and transcription factors (e.g., NRSF and Nkx2.5) involved in cardiac disease progression have been shown to regulate the expression of TTCCs in cardiomyocytes." (PMID 32684070, 2020). "In the general population, CHF is a complex syndrome associated with multiple endocrine alterations, including low IGF-1 levels, GHD, and a condition of GH resistance that may be related to the severity of heart disease and the pathogenesis of these alterations is still being debated." (PMID 30356378, 2018). "While our data on serum IGF-1 and 3-MH levels in HCM-affected cats are largely similar to what has been previously found in studies in human and veterinary medicine on these markers in the context of heart disease, the role of 26S PSM could not be assessed conclusively in this context." (PMID 40427314, 2025).